LEP (leptin)
Diseases named in the same sentence as LEP in open-access papers (continued):
Sharing a sentence is not in itself a finding about the gene and the disease.
Obesity (continued). "The defect in the ob gene contributes to suppressed leptin production and, ultimately, causes diabetes and development of severe obesity." (PMID 35011070, 2021). "The decreased level of adiponectin and increased levels of leptin, c-peptide, insulin and angiopoietin-like 3 protein were associated with metabolically healthy and unhealthy obesity." (PMID 34947881, 2021). "Data have suggested that dysregulated leptin is usually associated with metabolic diseases, including obesity and T2DM." (PMID 34446063, 2021). "Thbs1 -/- mice are resistant to obesity following ingestion of a high-fat diet and display normal levels of leptin, an important adipokine associated with increased body weight." (PMID 33854480, 2021). "Obesity itself is described to promote inflammation, and it is associated with insulin and leptin resistance, which contribute to higher blood insulin and leptin levels." (PMID 34829950, 2021). "High leptin levels caused by obesity in patients with PWS can lead to an increased conversion of T4 to T3." (PMID 34501256, 2021). "Since elevated leptin levels in obese patients do not lead to decreased food intake and increased energy expenditure, the obesity-associated hyperleptinemia is thought to reflect leptin resistance." (PMID 34680216, 2021). "The significant alternations in leptin concentration in the serum are suspected to be associated with obesity." (PMID 33809784, 2021). "Despite the anorexigenic effect of leptin, obesity is often associated with elevated leptin levels, indicating leptin resistance." (PMID 35047549, 2021). "Our results suggest that high-load exercise aggravates the inflammatory response of the hypothalamus caused by obesity and counteracts the upregulation of kisspeptin in the hypothalamus by improving leptin resistance." (PMID 33472656, 2021). "Though, its involvement in obesity is still uncertain, several animal and clinical studies have demonstrated that increased plasma levels of leptin are associated with high body mass and atherosclerosis." (PMID 33854480, 2021). "Our study provided new evidence suggesting the key role of leptin in mediating obesity-related OA process and its underlying mechanisms." (PMID 34457118, 2021). "Among these, adiponectin and leptin have received special attention as molecular mediators in the association between obesity and breast cancer." (PMID 34485137, 2021). "Within the hypothalamus, the dorsomedial hypothalamus (DMH) was also shown to be involved in the increase in BP caused by higher leptin levels in diet-induced obesity, possibly via MC4R." (PMID 34512392, 2021). "Meanwhile, infectious complications are often comorbid with diabetes and obesity, which are characterized by insulin resistance and leptin signaling deficiency." (PMID 34795562, 2021). "BPH/5 females have pre-existing cardiometabolic risk, including hyperphagia, obesity and leptin resistance, and hypoestrogenemia, before pregnancy and their phenotype is unique from BPH/5 males." (PMID 34270549, 2021). "Biochemical markers in cord blood such as leptin are easy to measure and are potentially useful for risk stratification of children at birth for obesity and other related cardiometabolic disorders in later life." (PMID 33669328, 2021). "Obesity is an established risk factor for breast cancer in post-menopausal women, being associated with elevated serum levels of leptin." (PMID 33644151, 2021). "In contrast, some taxa that were increased in Veh mice, including Streptococcaceae and its genus Lactococcus, were positively associated with body weight, fat mass, and leptin, suggesting these taxa are predictors of obesity." (PMID 34436440, 2021). "Leptin-deficient ob/ob mice and leptin receptor-deficient db/db mice are commonly used mice models mimicking the conditions of obesity and type 2 diabetes development." (PMID 34183063, 2021).
Obesity (continued). "Human obesity is also frequently associated with resistance to both leptin and insulin, and genome-wide association studies have implicated mutations near the melanocortin receptor-4 in the development of obesity and insulin resistance." (PMID 34604220, 2021). "Its overexpression occurring in obesity leads to increased susceptibility to autoimmunity and chronic inflammation, evidencing the role of leptin as a pro-inflammatory hormone." (PMID 33673730, 2021). "Several potential obesity candidate genes and variants have been documented, including LEP and LEPR, which have been mainly implicated in monogenic obesity, as well as FTO, APOE, PPARG, and PPARA which have been mainly implicated in polygenic/common obesity." (PMID 34131278, 2021). "This review provides a summary of recent in vivo and in vitro studies that highlight a role of leptin in the pathogenesis of atherosclerotic complications associated with obesity and diabetes." (PMID 34064112, 2021). "Cardinal symptoms of congenital leptin deficiency due to LEP -/- variants include severe early-onset obesity, hyperphagia, and disturbance gonadotropic function." (PMID 34448070, 2021). "Leptin enhances airway resistance, whereas loss of leptin can enhance airway resistance due to obesity." (PMID 34074279, 2021). "Leptin, a polypeptide product of a gene associated with obesity, can decrease food intake while increasing energy expenditure." (PMID 34070274, 2021). "Leptin is considered one of the main explanations of the association between obesity and OSAS, since obese subjects show resistance to leptin function." (PMID 33669035, 2021). "Mice deficient in the leptin gene, termed ob/ob mice, develop spontaneous obesity due to dysregulated hyperphagia when fed a chow diet, and as such are a common model of genetic obesity." (PMID 35046901, 2021). "The purpose of this study was to elucidate the pathogenesis of obesity-associated asthma by focusing on the interaction between leptin and IL-33." (PMID 34074279, 2021). "Genetic STAT3 null or STAT3 phosphorylation deficiency in hypothalamus causes central leptin resistant and severe obesity animal." (PMID 33849593, 2021). "Increased fat mass in obesity causes chronic inflammation and increases the expression of numerous adipokines, including leptin." (PMID 33935782, 2021). "Obesity indices were associated with leptin and CRP in the third and fourth quartiles in single models." (PMID 33680494, 2021). "Non-coding RNAs have been implicated in the regulation of leptin gene expression, with its dysregulation linked to obesity and in the development of hypothalamic leptin insensitivity." (PMID 34084149, 2021). "In breast cancer, the associated genes of obesity collectively lead to an increase in fat mass and production of cytokines such as leptin, which has been associated with a higher risk of cancer development." (PMID 34212054, 2021). "Mechanical effects of visceral fat on natriuresis, leptin-mediated sympathetic nervous system activation as well as increased renin-aldosterone action likely contribute to obesity-associated hypertension." (PMID 34760952, 2021). "We evaluated the influence of leptin in the association between obesity and NEFA concentrations in children, analyzing two cohorts including 684 6- to 8-year-olds and 836 12- to 16-year-old children, respectively." (PMID 35071145, 2021). "The anorexigenic hormone leptin induces satiety and weight loss, whereas leptin resistance in obesity contributes to hyperphagia and weight gain." (PMID 34192532, 2021). "Similar findings have also been observed in models of induced obesity and type 2 diabetes using the leptin‐deficient mouse (ob/ob) as well as high‐fat diet." (PMID 33532621, 2021). "Leptin is a hormone with a molecular weight of 16 kDa that is encoded by the obesity gene (OB), located on chromosome 7 in humans, that transcribes for a 167 amino acids long peptide with a 21-amino acid signal sequence at the amino-terminus." (PMID 34356668, 2021).
Obesity (continued). "Increased leptin signaling was causally linked to obesity-associated TNBC development by promoting CSC enrichment and EMT." (PMID 34350120, 2021). "A combination of higher levels of leptin under obese conditions and increased expression of Ob-R in breast cancer cells further suggests a vital role of leptin in obesity-associated breast cancer." (PMID 34944905, 2021). "Loss of function of LEPR is associated with the elevated leptin levels and obesity, showing its participating in adipose biogenesis." (PMID 33807688, 2021). "Obesity is associated with excessive free fatty acids, cholesterol, triglycerides, hormones such as leptin, interleukins, and chemokines, which all have roles in breast cancer development." (PMID 34912237, 2021). "The involvement of LEP in lifestyle-diseases risk factors (through obesity pathophysiological pathways) also supports the possible impact of the environment and epigenetic pathways in LEP function and/or regulation." (PMID 34884678, 2021). "Mutations within leptin or the leptin receptor cause early-onset obesity and hyperphagia, as described in human and animal models." (PMID 33922961, 2021). "Better characterized is the role of leptin signaling in obesity-associated low-grade systemic inflammation." (PMID 33922372, 2021). "A partial reduction of plasma leptin level by leptin neutralizing antibody in obesity state improved leptin sensitivity and effectively led to weight loss and enhanced insulin sensitivity." (PMID 34084149, 2021). "Increased circulating leptin levels are typical in obesity and are independently associated with CVD risk in humans." (PMID 34947881, 2021). "Mutations in leptin and the Lepr have been shown to cause early-onset severe obesity in mice and humans." (PMID 34390703, 2021). "We identified hyperleptinemia and leptin resistance in patients with menstrual function impairment associated with obesity." (PMID 35126755, 2021). "The third strongest signal was observed closest to the MC4R gene (index SNP rs663129, Pmeta = 3.10 × 10− 18), which is involved in the leptin signaling pathway and its disruption is a causal factor of obesity." (PMID 33910581, 2021). "Some adipokines, such as leptin, resistin, and visfatin, which are overproduced in obesity and widely implicated in different stages of cancer, promote cellular glucose and lipid metabolism." (PMID 33535537, 2021). "Leptin, which is encoded by the obesity gene (Ob) and secreted primarily by WAT, is directly related to obesity." (PMID 34016950, 2021). "In the discovery stage, we identified that DNA methylation-associated LEP expression was correlated with prognosis among obesity-related genes from the databases of The Cancer Genome Atlas." (PMID 33485366, 2021). "Leptin deficiency-associated obesity is resolved upon treatment with recombinant leptin, strongly indicating the critical physiological roles of leptin and leptin signaling in the control of body energy homeostasis." (PMID 34211092, 2021). "Various approaches, including lung function and adipokines such as leptin, have been used to understand the pathogenesis of obesity-associated asthma." (PMID 34074279, 2021). "Based on literature, there is a complicate association between zinc and leptin in obesity conditions." (PMID 34631042, 2021). "Associated with the pathophysiology of obesity-related metabolic dysfunctions arehyperleptinemia and hyperinsulinemia, and body adiposity in obesity is relative toinsulin and leptin levels in the circulation." (PMID 34879109, 2021). "Obesity is linked with an elevation of the levels of leptin and chronic immune-mediated inflammation." (PMID 33670130, 2021). "The genetic screening of 73 children with early-onset obesity and hyperphagia from Pakistani consanguineous families identified 14 subjects carrying LEP variants, including two siblings homozygous to p.Arg105Trp." (PMID 34504472, 2021).
Obesity (continued). "Genetically modified obese mice have also been used to investigate the association between obesity and BC, with particular attention paid to leptin involvement and its controversial activity." (PMID 33572982, 2021). "Pediatric populations with obesity tend to follow a similar pattern since a recent study underlined that leptin, IL6, and TNF α serum levels significantly correlate to body mass index in children with obesity." (PMID 34207683, 2021). "Among them, leptin is positively associated with obesity, fat mass, insulin resistance, triglyceride levels, and inflammatory cytokines and negatively associated with high-density lipoprotein cholesterol." (PMID 34368053, 2021). "Clinically, individuals with obesity and increased levels of leptin have been characterized as leptin-resistant; meanwhile, the loss of leptin-LepRl signaling in the brain has shown to be sufficient to promote obesity." (PMID 34884416, 2021). "What is more, some research indicates that there is also a significant correlation between enhanced levels of leptin and developing cancer associated with obesity." (PMID 33809784, 2021). "During the last decades, obesity and leptin have been associated with the initiation, proliferation and progression of many types of cancer." (PMID 34202969, 2021). "Inflammation is associated with anorexia and appetite loss (Gautron and Layé, 2010; Braun and Marks, 2010), yet chronic inflammation has been linked to the development of obesity by mechanisms involving leptin resistance and appetite increase." (PMID 34661243, 2021). "SARS-CoV-2 mediated leptin expression promotes inflammatory respiratory diseases, which link obesity and leptin as risk factors in COVID-19." (PMID 35052684, 2021). "Body fat is well associated with leptin levels and an excess level of leptin due to hyperleptinemia is a characteristic of obesity." (PMID 32272767, 2020). "Leptin has been implicated in a number of immune-mediated diseases, many of which are also associated with obesity." (PMID 33584724, 2020). "The Zucker rat has defective leptin signaling due to a mutation in the leptin receptor which results in hyperphagic obesity, in which reduced lipid oxidation contributes to the obese state." (PMID 32326226, 2020). "We studied the effects of IL-4 on metabolic abnormalities in a mice model of obesity involving leptin deficiency and leptin resistance." (PMID 32585823, 2020). "We next sought to confirm our above findings obtained from the diet-induced model of obesity by using the ob/ob leptin-deficient genetic mouse model of metabolic syndrome." (PMID 32728158, 2020). "Mutations that disrupt the leptin–melanocortin pathway are associated with severe obesity in both rodents and humans." (PMID 33233816, 2020). "Leptin, a hormone that regulates food intake and energy balance and is overexpressed in obesity, has been implicated as a link between breast cancer and obesity, which represents a risk factor for breast cancer." (PMID 33213024, 2020). "High levels of circulating leptin caused by obesity has been shown to lead to leptin resistance in the hypothalamus and is linked to altered metabolism, inflammation, and neurodegeneration in the brain." (PMID 33414704, 2020). "Mutations in leptin or the leptin receptor gene cause early onset extreme obesity, hyperphagia, hypogonadism, and metabolic disorders." (PMID 33584724, 2020). "Leptin is one of the several factors that can explain the underlying association between obesity and TD." (PMID 33179018, 2020). "Monogenic obesity due to homozygous mutations in the leptin gene is a rare autosomal recessive disorder, leading to severe early-onset obesity and congenital circulating leptin deficiency." (PMID 33261141, 2020). "Leptin is an obesity-associated hormone that promotes vascular smooth muscle cell (VSMC) hypertrophy." (PMID 32566092, 2020).
Obesity (continued). "Although obesity is classically a cause of secondary hypogonadism, the frequently elevated concentration of leptin in these individuals appears to directly affect testicular function." (PMID 33179018, 2020). "Its function was described as a protector against obesity because the ob/ob mice (leptin-deficient) and db/db mice (leptin-resistant) were obese, among other signs and symptoms." (PMID 32839413, 2020). "The leptin-deficient ob/ob mouse is a widely used model to study obesity and largely resembles congenital leptin deficiency in humans." (PMID 32655492, 2020). "In dogs, several reports indicated that the level of leptin in serum correlates with obesity scale and decreases with weight loss." (PMID 32851001, 2020). "Murine models with mutations in either leptin or the leptin receptor gene led to body fat accumulation, and the onset of obesity and diabetes mellitus." (PMID 32578019, 2020). "Mutations in gene encoding leptin or the leptin receptor are reported to cause severe obesity, hyperphagia, and insulin resistance." (PMID 33113859, 2020). "It has been reported that changes in epigenetic modification of leptin and adiponectin genes are associated with occurrence of obesity and other metabolic diseases." (PMID 32586265, 2020). "Although global research has been done on the association between leptin, obesity and insulin resistance, however, as per our knowledge, there is no local data available regarding this subject in the Pakistani population." (PMID 33489589, 2020). "In contrast, a high-fat diet can induce the HMGA2 expression in adipose tissues and cause obesity in wild-type and leptin-deficient mice." (PMID 32466162, 2020). "In summary, both obesity and adipocytes’ repletion have been associated with an imbalance in adipokines’ serum concentration, increasing pro-inflammatory adipokines such as leptin or resistin, and decreasing anti-inflammatory cytokines such as adiponectin." (PMID 32630168, 2020). "Previous studies showed a positive association between obesity and leptin and resistin concentrations." (PMID 33007981, 2020). "Several attempts have been made to show a possible association between leptin and LepR polymorphisms and metabolic disturbances leading to obesity." (PMID 32069871, 2020). "Within adipose tissue, adipocytes have also been shown to regulate angiogenesis through the secretion of adipokines, and adipokine secretion, including leptin, has been implicated in tumor angiogenesis in the context of obesity." (PMID 32098183, 2020). "The concentration of adipokines, such as TNF-α, IL-6 and leptin, were significantly higher in obese subjects and the elevated levels was linked to obesity, and even positively correlated with body mass index." (PMID 32819324, 2020). "In some of our previous studies, we also reported gender-specific association of the other variants such as MC4R rs17782313, FTO rs9939609, and LEP rs7799039 with overweight/obesity and related anthropometric traits in Pakistani females." (PMID 32419576, 2020). "Leptin is also known to be one of the key factors associated with the development of obesity-induced hypertension, acting both centrally and peripherally." (PMID 32756352, 2020). "Adipokines, such as leptin and adiponectin, as well as other circulating factors such as insulin are associated with “metabolic syndrome” and have been extensively studied in obesity-linked OA." (PMID 32295649, 2020). "Obesity caused by leptin deficiency or high-fat feeding in mice induces ER stress in peripheral tissues as well as in the hypothalamus." (PMID 32163401, 2020). "This seemingly counterintuitive observation is partially supported by data suggesting complex associations of obesity/adiposity, LEP/LEPR’s activation of various signaling pathways, and breast cancer progression, which is further complicated by ER expression." (PMID 32046756, 2020).